RFX5 (regulatory factor X5)
Description:
Activates transcription from class II MHC promoters. Recognizes X-boxes. Mediates cooperative binding between RFX and NF-Y. RFX binds the X1 box of MHC-II promoters.
Synonyms: MHC2D3; MHC2D5
Tractability: PROTAC: ubiquitination databases record sites on it; its protein half-life has been measured.
Gene: Protein-coding gene on chromosome 1 (151,340,640 to 151,347,339, reverse strand). Ensembl gene ENSG00000143390.
Subcellular location: Nucleus
Subcellular location (Human Protein Atlas): Nucleoplasm; Vesicles
Gene Ontology:
Molecular function: DNA-binding transcription activator activity, RNA polymerase II-specific; protein binding; RNA polymerase II transcription regulatory region sequence-specific DNA binding; sequence-specific DNA binding; sequence-specific double-stranded DNA binding; transcription coregulator binding; DNA-binding transcription factor activity, RNA polymerase II-specific; RNA polymerase II cis-regulatory region sequence-specific DNA binding; DNA binding; DNA-binding transcription factor activity
Biological process: positive regulation of MHC class II biosynthetic process; positive regulation of transcription by RNA polymerase II; regulation of transcription by RNA polymerase II; regulation of DNA-templated transcription
Cellular component: nucleoplasm; nucleus; RNA polymerase II transcription regulator complex; chromatin
Genetic constraint (gnomAD): Loss-of-function variants: 33 observed, 49.94 expected, observed/expected ratio (o/e) 0.66, 90% interval 0.5 to 0.88. The synonymous counts are far from expectation, so gnomAD's model fits this gene poorly and the ratio says little. Missense variants: 714 observed, 815.51 expected, observed/expected ratio (o/e) 0.88, 90% interval 0.82 to 0.93. Synonymous variants: 231 observed, 309.29 expected, observed/expected ratio (o/e) 0.75, 90% interval 0.67 to 0.83.
Gene-disease validity (ClinGen):
ClinGen rates the evidence that RFX5 causes each of these diseases.
MHC class II deficiency (autosomal recessive): Definitive.
Homologues: Orthologues: chimpanzee RFX5 (99% identical), macaque RFX5 (97% identical), pig RFX5 (88% identical), guinea pig RFX5 (86% identical), dog RFX5 (86% identical), rabbit RFX5 (84% identical), rat Rfx5 (80% identical), mouse Rfx5 (78% identical), tropical clawed frog rfx5 (37% identical), zebrafish rfx5 (34% identical), Drosophila melanogaster CG9727 (20% identical). Paralogues in human: RFX7 (31% identical), RFX1 (15% identical), RFX2 (14% identical), RFX3 (13% identical), RFX4 (11% identical), RFX6 (11% identical), RFX8 (5% identical).
Diseases named in the same sentence as RFX5 in open-access papers:
RFX5 is named in the same sentence as 31 diseases in open-access papers, as found by Europe PMC text mining. Sharing a sentence is not in itself a finding about the gene and the disease. The quoted sentences say what the papers report.
bare lymphocyte syndrome (7 papers, 2008 to 2026). "We also find RFX5, a transcription factor involved in primary MHC class II deficiency, to discriminate between hmC symmetries in CpG dyads." (PMID 41486423, 2026). "Major histocompatibility complex class II (MHC II) deficiency (bare lymphocyte syndrome type II) is an autosomal-recessive combined immunodeficiency caused by pathogenic variants in the transcriptional regulators CIITA, RFXANK, RFX5, or RFXAP." (PMID 41376631, 2025). "Five children (13.9%) were identified with a defect in MHC class II expression—bare lymphocyte syndrome (BLS), and this was accounted for by variants in CIITA (n = 3), RFXANK (n = 1), and RFX5 (n = 1)." (PMID 33519828, 2020). "A fourth RFX gene (RFX4) was discovered in a human breast tumor tissue and the fifth, RFX5, was identified as a DNA-binding regulatory factor that is mutated in primary MHC class II deficiency (bare lymphocyte syndrome, BLS)." (PMID 18673564, 2008). "Mutation in any one of the RFX5 enhanceosome members–RFXANK, RFXAP, CREB, and CIITA–leads to bare lymphocyte syndrome (BLS)." (PMID 18673564, 2008).
Immunodeficiency (5 papers, 2021 to 2025). Failure of the immune system to protect the body adequately from infection, due to the absence or insufficiency of some component process or substance. "Regulatory factor X-5 (RFX5) is involved in regulation of major histocompatibility class II and RFX5 mutations result in immunodeficiency." (PMID 40971994, 2025). "The compound heterozygous splicing mutations of RFX5: c.353 + 6T>G (maternally inherited) and c.757 + 1G>A (paternally inherited) were identified in an infant diagnosed severe immunodeficiency." (PMID 36276949, 2022). "Mutations in RFX5 in humans lead to severe immunodeficiency, but, interestingly, mutations in the similar protein RFX6 cause malformations of the gut." (PMID 34020589, 2021). "For example, in subclusters of osteo-like, basal/stromal, and endothelial cells, regulatory factor X (RFX5, RFXAP, and RFXANK) can mediate their immunodeficiency function by binding domains of RFX- and NFX-." (PMID 35237614, 2021).
breast carcinoma (4 papers, 2018 to 2025). "Studies have reported that CELSR2, ETV6, MGAT1, and RFX5 were associated with breast cancer." (PMID 35071020, 2021). "Besides, RFX5 was tested to express differentially in breast cancer." (PMID 29713243, 2018). "Compared with normal breast epithelium cells, the expression levels of RFX5, VEGFA were significantly upregulated in breast cancer cells." (PMID 40520263, 2025). "RFX5 can strongly increase transcriptional activity of LINC00504 and the latter is upregulated in breast cancer." (PMID 35071020, 2021). "Compared with normal breast epithelium cells, RFX5, VEGFA were upregulated in breast cancer cells, IKZF2, NAB1, S100B were downregulated in breast cancer cells while F2R, S1PR2 showed no significance." (PMID 40520263, 2025).
hepatocellular carcinoma (4 papers, 2018 to 2025). A malignant tumor that arises from hepatocytes. "RFX5 promotes cell cycle progression and inhibits apoptosis in hepatocellular carcinoma." (PMID 38294290, 2024). "Furthermore, analysis of genomics data derived from the TCGA Liver hepatocellular carcinoma (LIHC) revealed regulatory factor X-5 (RFX5), located in the chromosome 1q21 loci, have aberrantly raised expressions in HCC patients." (PMID 32883983, 2020). "In summary, RFX5 transcriptionally activates KDM4A expression, which drives hepatocellular carcinoma progression by inhibiting apoptosis, accelerating cell cycle transition and subsequently promoting HCC development." (PMID 32883983, 2020). "As to RFX5 (Regulatory Factor X), being able to bind DNA and lend promoter specificity, was identified as a transcriptional activator of the TPP1 gene in hepatocellular carcinoma." (PMID 29713243, 2018).
combined immunodeficiency (3 papers, 2012 to 2025). A broad classification of inherited disorders presenting at birth that affect both the cell-mediated and humoral aspects of the immune response. "Genetic studies of patients with combined immunodeficiency (CID) with predominant CD4 cell deficiency have revealed mutations in genes encoding regulatory factors of the expression of MHC class II molecules such as CIITA, RFXANK, RFX5 or RFXAP." (PMID 25205547, 2014).
MHC class II deficiency (3 papers, 2022 to 2026). Immunodeficiency by defective expression of HLA class 2 is a rare primary genetic immunodeficiency disorder characterized by partial or complete absence of human leukocyte antigen class 2 expression resulting in severe defect in both cellular and humoral immune response to antigens. "There was one case of MHC Class II deficiency, also called Bare lymphocyte syndrome type 2 (due to a homozygous RFX5 variant)." (PMID 40061245, 2025).
autoimmune disease (2 papers, 2014 to 2018). A disorder resulting from loss of function or tissue destruction of an organ or multiple organs, arising from humoral or cellular immune responses of the individual to their own tissue constituents. "Transcription factors NFKB1 and RFX5 are each associated with three and six autoimmune disorders, while both TFs are known to be involved in autoimmunity." (PMID 29325558, 2018).
psoriasis (2 papers, 2014 to 2025). An autoimmune condition characterized by red, well-delineated plaques with silvery scales that are usually on the extensor surfaces and scalp. "Case with psoriasis has homozygous DCLRE1C, heterozygous ZAP70, RFX5, AKT1, and NOD2 gene variants, and all of them were VUS variants." (PMID 39992598, 2025).
stomach adenocarcinoma (2 papers, 2022 to 2025). "Previous studies have shown that RFX5 is involved in the occurrence and development of several human tumors, such as stomach adenocarcinoma and non‐small cell lung cancer." (PMID 39718123, 2025).
allergic disease (1 paper, 2020). An immune response that occurs following re-exposure to an innocuous antigen, and that requires the presence of existing antibodies against that antigen. "STAT1, STAT3, TLR8, IL13, RFX5 gene polymorphisms have been demonstrated as susceptibility loci for the immune dysregulation in various inflammatory and allergic diseases." (PMID 32886659, 2020).
Brain atrophy (1 paper, 2019). Partial or complete wasting (loss) of brain tissue that was once present. "We speculated that NNT and RFX5 may be involved in the secretion of insulin and the abnormity of these loci may be related to the whole brain atrophy, leading to the enlargements of ventricular system structures in AD." (PMID 31775305, 2019).
brucellosis (1 paper, 2024). Brucellosis is a bacterial infection that spreads from animals to people via unpasteurized dairy products or by exposure to contaminated animal products or infected animals. "In agreement with this, the expression levels of phagocytosis‐ and antigen‐presentation‐associated genes (e.g., CIITA, RFX5, HLA‐DPA1, WASF2) were reduced in brucellosis patients." (PMID 39135683, 2024).
cutaneous melanoma (1 paper, 2022). A primary melanoma arising from atypical melanocytes in the skin. "Lastly, we treated three cutaneous melanoma cell lines with Nutlin-3 for 24 h and investigated the mRNA expression of RFX7, RFX5, PNRC1, PDCD4 and CDKN1A as positive control." (PMID 36139642, 2022).
gastric cancer (1 paper, 2021). A primary or metastatic malignant neoplasm involving the stomach. "Using RNA-seq data from 400 gastric cancer patients, the upregulation of all MHC-II involved genes, including CIITA and RFX5, was observed compared to normal tissues or other types of gastric cancers." (PMID 33499042, 2021).
head and neck carcinoma (1 paper, 2019). A carcinoma that arises from the head and neck region. "Thus, the upregulated expression of CIITA, RFX5, and subsequent expression of all the classical MHC-II genes and related genes required for antigen loading and presentation observed in HPV+ head and neck carcinomas are likely a consequence of IFNγ exposure." (PMID 31394808, 2019).
liver cirrhosis (1 paper, 2017). "Our results also uncovered several other TFs that may regulate the process of liver cirrhosis (e.g. FOXA1, RFX5, and ETS1) which are new potential targets for mechanistic studies of liver cirrhosis." (PMID 28355233, 2017).
myeloma (1 paper, 2021). "Six TFs (CXXC1, BPTF, MAZ, KLF13, CBFB and RFX5) were identified as showing higher connectivity in all myeloma subgroups compared to ND PC, thus exemplifying the process of existing TF ‘re-wiring’ in MM." (PMID 34521827, 2021).
rheumatoid arthritis (1 paper, 2023). A chronic, systemic autoimmune disorder characterized by inflammation in the synovial membranes and articular surfaces. "Interestingly, RFX5 was recently reported to enhance surface expression of HLA-DR molecules, which promoted tissue macrophages-dependent expansion of antigen-specific T cells in rheumatoid arthritis." (PMID 37008925, 2023).
Sepsis (1 paper, 2021). Sepsis is defined as life-threatening organ dysfunction caused by a dysregulated host response to infection. "In our analysis, we found that K. pneumoniae TTF, RFX5 severely downregulated in K. pneumoniae positive sepsis patients." (PMID 33679637, 2021).
type 2 diabetes (1 paper, 2022). "Additionally, the expression of HLA-DRB1 is also predictive of type 2 diabetes, as is the expression of CIITA and another HLA-DRB1 TF, RFX5, which determine susceptibility to type 2 diabetes mellitus." (PMID 35627314, 2022).
tumor (11 papers, 2020 to 2025). "Another vital finding of our study was that RFX5 expression was significantly associated with the abundance of immune cells, the expression of immune biomarkers and tumor mutational burden score in STAD." (PMID 36045400, 2022). "A heterozygous non-synonymous mutation (D59N) in transcription factor RFX5 was also described in DFT2 tumours." (PMID 36259237, 2022). "Consistently, Kaplan–Meier survival analysis showed high expression of RFX5 proteins stained by IHC in primary HCC tumor tissue was associated with poor overall survival (P = 0.0176) of patients with advanced HCC in Guilin cohort." (PMID 32883983, 2020). "Moreover, RFX5 expression was significantly associated with the abundance of immune cells, the expression of immune biomarkers and tumor mutational burden score in STAD." (PMID 36045400, 2022). "A functional study demonstrated that HCC cell colony formation and subcutaneous tumor growth were dependent on RFX5 overexpression." (PMID 32883983, 2020). "RFX5 was found to be significantly overexpressed in HCC tumor tissues by bioinformatics analysis." (PMID 39718123, 2025). "Interestingly, RFX5 mRNA has previously been shown overexpressed in HCC compared with non-tumor tissue, which promoted HCC progression via transcriptionally activating KDM4A, TPP1 and YWHAQ." (PMID 37008925, 2023). "However, overexpression of KDM4A in RFX5 depleted cells significantly recovered the tumor growth potential that was compromised by RFX5 knockdown." (PMID 32883983, 2020). "These evidences revealed that RFX5 may play a vital role in the tumor microenvironment of STAD." (PMID 36045400, 2022). "In HCC, RFX5 binds to the promoter region of KDM4A to upregulate the expression of KDM4A, thereby inhibiting tumor apoptosis and promoting cell cycle progression." (PMID 39718123, 2025). "IHC experimental results indicated that knocking down RFX5 significantly inhibited the protein expression of RFX5 and STIL in tumor tissues, while further overexpression of STIL reversed the inhibitory effect of RFX5 knockdown on STIL protein expression without affecting RFX5 protein expression." (PMID 39718123, 2025). "CIITA and RFX5, two important activators of transcription of MHC-II pathway genes that are regulated by IFNγ, are highly upregulated in EBVaGCs and their expression is strongly correlated with IFNG across individual tumor samples." (PMID 32901107, 2020). "Furthermore, regulatory factor X5 (RFX5), a key regulator of MHC class II molecule expression, connects adaptive immunity through non-classical antigen presentation functions, and its heightened activity in CD8+ TEM cells may play a pivotal role in orchestrating their anti-tumor responses." (PMID 41155287, 2025). "However, RFX5 overexpression in HCC cell lines and tumor tissues failed to provoke a tangible response in MHCII expression, suggesting that other, non-MHCII target genes may be involved in HCC progression." (PMID 32883983, 2020).
cancer (8 papers, 2020 to 2025). A tumor composed of atypical neoplastic, often pleomorphic cells that invade other tissues. "The regulation of these genes’ expression by RFXANK, RFXAP, and RFX5 TFs has been pointed across 18 different cancer types." (PMID 40226614, 2025). "Additionally, 46 out of the 49 TFs are known to play roles in CRC and the remaining three (RFXAP, SPI1 and RFX5) are related to other cancers." (PMID 36760999, 2023). "Notably, the cellular localization and distribution patterns of KDM4A protein were highly consistent with that of RFX5 protein in the continuous sections of the same cancer nest." (PMID 32883983, 2020). "Other important positive biomarkers shared across all 18 cancer types were RFXANK, RFXAP, and RFX5, which form the RFX trimeric complex." (PMID 34430923, 2021). "In this study, we found that RFX5 was highly expressed in HCC and could activate STIL expression by regulating glycolysis to promote cancer cell stemness." (PMID 39718123, 2025).
infection (4 papers, 2016 to 2025). The state of being infected such as from the introduction of a foreign agent such as serum, vaccine, antigenic substance or organism. "At 3 days post-infection (DPI 3), we confirmed the successful overexpression of RFX2, RFX3, RFX4, and RFX5 in stem cells." (PMID 38386071, 2024). "CPAF, residing in the host cell cytoplasm during infection is responsible for degrading USF-1 and Regulatory Factor X5 (RFX5) proteins." (PMID 31467721, 2019).
infectious disease (1 paper, 2014). A disorder directly resulting from the presence and activity of a microbial, viral, or parasitic agent in humans. "Our study has demonstrated that CIITA recruitment commonly occurs outside the MHC, often not in the setting of a classical enhanceosome with RFX5, and involves genes enriched for immune function and infectious disease." (PMID 25366989, 2014).
RFX5 also shares sentences with these, for which no sentence is quoted: viral infection (3 papers); Autoimmunity (1); cervical cancer (1); lymphoid cancers (1); non-small cell lung carcinoma (1); type 2 diabetes mellitus (1); uveal melanoma (1).